HNRNPC (heterogeneous nuclear ribonucleoprotein C)
Description:
Binds pre-mRNA and nucleates the assembly of 40S hnRNP particles. Interacts with poly-U tracts in the 3'-UTR or 5'-UTR of mRNA and modulates the stability and the level of translation of bound mRNA molecules. Single HNRNPC tetramers bind 230-240 nucleotides. Trimers of HNRNPC tetramers bind 700 nucleotides. May play a role in the early steps of spliceosome assembly and pre-mRNA splicing. N6-methyladenosine (m6A) has been shown to alter the local structure in mRNAs and long non-coding RNAs (lncRNAs) via a mechanism named 'm(6)A-switch', facilitating binding of HNRNPC, leading to regulation of mRNA splicing.
Synonyms: HNRPC; HNRNP; MRD74; SNRPC
Tractability: PROTAC: UniProt records ubiquitination sites on it; ubiquitination databases record sites on it; its protein half-life has been measured.
Target class: Other nuclear protein
Gene: Protein-coding gene on chromosome 14 (21,207,375 to 21,269,792, reverse strand). Ensembl gene ENSG00000092199.
Subcellular location: Nucleus
Subcellular location (Human Protein Atlas): Nucleoplasm
Pathways (Reactome):
Metabolism of RNA: Processing of Capped Intron-Containing Pre-mRNA; mRNA Polyadenylation; mRNA Splicing - Major Pathway
Signal Transduction: RHOBTB1 GTPase cycle; RHOBTB2 GTPase cycle
Disease: Dengue Virus-Host Interactions
Metabolism of proteins: SUMOylation of RNA binding proteins
Gene Ontology:
Molecular function: identical protein binding; mRNA 3'-UTR binding; N6-methyladenosine-containing RNA reader activity; nucleosomal DNA binding; poly(U) RNA binding; protein binding; RNA binding; telomerase RNA binding; nucleic acid binding
Biological process: 3'-UTR-mediated mRNA stabilization; chromatin remodeling; mRNA splicing, via spliceosome; negative regulation of telomere maintenance via telomerase; osteoblast differentiation; RNA splicing
Cellular component: actin cytoskeleton; catalytic step 2 spliceosome; chromatin; cytosol; extracellular exosome; extracellular region; membrane; nucleoplasm; nucleus; protein-containing complex; spliceosomal complex; telomerase holoenzyme complex
Genetic constraint (gnomAD): Loss-of-function variants: 3 observed, 29.41 expected, observed/expected ratio (o/e) 0.1, 90% interval 0.045 to 0.26. The upper end of that interval is the gene's LOEUF score, 0.26, which puts it in group 1 of 6, group 1 being the genes least tolerant of losing a copy. Missense variants: 131 observed, 353.88 expected, observed/expected ratio (o/e) 0.37, 90% interval 0.32 to 0.43. Synonymous variants: 113 observed, 120.91 expected, observed/expected ratio (o/e) 0.93, 90% interval 0.8 to 1.09.
Homologues: Orthologues: chimpanzee HNRNPC (100% identical), macaque HNRNPC (100% identical), rabbit HNRNPC (99% identical), mouse Hnrnpc (98% identical), rat LOC100911576 (98% identical), tropical clawed frog hnrnpc (81% identical). Paralogues in human: HNRNPCL1 (91% identical), HNRNPCL2 (88% identical), HNRNPCL3 (88% identical), HNRNPCL4 (88% identical), RALYL (49% identical), RALY (46% identical).
Diseases named in the same sentence as HNRNPC in open-access papers:
HNRNPC is named in the same sentence as 112 diseases in open-access papers, as found by Europe PMC text mining. Sharing a sentence is not in itself a finding about the gene and the disease. The quoted sentences say what the papers report.
breast carcinoma (43 papers, 2019 to 2025). "We found that lower HNRNPC expression in breast cancer tumours was significantly associated with lower overall, disease-free and distant metastasis-free survival, both in individual cohorts and in meta-analyses." (PMID 37156909, 2023). "Increasing evidence suggested that up-regulation HNRNPC expression was associated with the occurrence and progression of tumors, such as breast cancer, gastric cancer, and glioblastoma." (PMID 37469973, 2023). "High expression of the m6A regulator hnRNPC, and low expression of hsa-miR-944, are associated with advanced stage breast cancer and poor prognosis." (PMID 35721510, 2022). "Heterogeneous nuclear ribonucleoprotein C could promote collagen fiber alignment and immune escape in breast cancer by activating vir like m6A methyltransferase associated-mediated TFAP2A/discoidin domain receptor tyrosine kinase 1 axis." (PMID 40813717, 2025). "In our model, PDLIM5 depletion impacts breast cancer progression due to HNRNPC deficiency." (PMID 37156909, 2023). "In addition, the reduced expression of HNRNPC and its regulon is associated with the worse prognosis in breast cancer patient cohorts." (PMID 37156909, 2023). "A recent study reported that hnRNPC deficiency induced type I IFN responses in breast cancer cells." (PMID 34297039, 2021). "High expression of HNRNPC has been found in many kinds of cancers and is always an indicator of poorer prognosis; this has been demonstrated in breast cancer, glioblastoma multiforme, and gastric cancer." (PMID 41154660, 2025). "Dysregulation of HNRNPC has been observed in lung cancer, breast cancer, and oral squamous cell carcinoma patients." (PMID 40549685, 2025). "Accumulating data indicate that HNRNPC participates in many tumor types such as breast cancer, colorectal cancer, and hepatocellular carcinoma." (PMID 38830885, 2024). "In line with PABPC4 acting together with HNRNPC, lower PABPC4 expression was associated with worse prognostic metrics and disease progression in breast cancer patient cohorts." (PMID 37156909, 2023). "To ensure that these findings are generalizable to other genetic backgrounds, we repeated the experiment with HCC1806 breast cancer cells and observed a consistent increase in the metastatic capacity of these cells upon HNRNPC downregulation." (PMID 37156909, 2023). "For instance, in two in vitro models of breast cancer the repression of heterogeneous nuclear ribonucleoprotein C (HNRNPC), a RBP, generated pre-mRNA introns that gave rise to dsRNA highly enriched in Alu elements belonging to HNRNPC binding sequences." (PMID 37180110, 2023). "Conversely, overexpressing HNRNPC in MDA-LM2 cells reduced the metastatic colonization by breast cancer cells." (PMID 37156909, 2023). "Previous studies have reported elevated levels of heterogeneous nuclear ribonucleoproteins C1/C2 (HNRNPC) in some cancer cells, while HNRNPC knockdown resulted in significant arrest of cell proliferation and tumour growth in breast cancer." (PMID 35277915, 2022). "Downregulation of hnRNPC, in particular, appears to significantly reduce protumorigenic properties of cancer cell lines via regulation of the interferon cascade pathway in breast cancer." (PMID 35355828, 2022). "In breast cancer, the high expression of hnRNPC is also observed, and the inhibition of this gene leads to the accumulation of double-stranded RNA (dsRNA)." (PMID 36051357, 2022). "A study showed that CircBACH2 sponged hsa-miR-944, which resulted in MAPK signaling pathway-dependent up-regulation of hnRNPC expression and promotion of breast cancer cell proliferation." (PMID 35721510, 2022). "Looking for a direct effect of Alu transcription, it is noteworthy that heterogeneous nuclear ribonucleoprotein C (HNRNPC) is essential in breast cancer cell survival by inhibiting the double-stranded-RNA (dsRNA)-induced interferon response." (PMID 36010599, 2022).
breast carcinoma (continued). "The overexpression of hnRNPc were related to poor prognosis in patients, but hnRNPc A2/B1 was reported to negatively regulate the metastasis of breast cancer." (PMID 35721510, 2022). "Elevated expression of heterogeneous nuclear ribonucleoprotein C (HNRNPC) has been reported in lung adenocarcinoma, breast cancer, and OSCC patients." (PMID 35963855, 2022). "Previous studies have described elevated levels of HNRNPC in some cancer cells, while HNRNPC knockdown has been shown to slow down cell proliferation and tumour growth in breast cancer." (PMID 35277915, 2022). "extended the function of HNRNPC to alternative splicing in breast cancer: by controlling endogenous double-stranded RNA, HNRNPC regulated the activation of the IFNβ signaling pathway to affect the progression of breast cancer." (PMID 33937074, 2021). "HNRNPC was highly expressed in bladder cancer, and the HNRNPC knockdown reduced the proliferation of breast cancer cells." (PMID 33628782, 2021). "HNRNPC, a splicing factor, is highly expressed in breast cancer and promotes tumour cell proliferation and growth." (PMID 34044876, 2021). "HNRNPC has been identified as an oncogene, enhancing deterioration in multiple tumor types, including gastric cancer, breast cancer, esophageal squamous cell carcinoma, and oral squamous cell carcinoma." (PMID 33937074, 2021). "Abnormal increased expression of HNRNPC was observed in multiple types of tumors, including breast cancer, lung cancer, glioblastoma, and hepatocellular carcinoma." (PMID 34281544, 2021). "HNRNPC knockdown arrested the proliferation of breast cancer cell lines via activating the antitumor cascade of interferon response initiated by the cytoplasmic RNA sensors retinoic acid-inducible gene I (RIG-I)." (PMID 34804925, 2021). "Repression of HNRNPC in breast cancer cells MCF7 and T47D was reported to inhibit cell proliferation and tumor growth." (PMID 33510252, 2021). "Heterogeneous nuclear ribonucleoprotein C (HNRNPC), a key m6A modification “Reader”, has been confirmed to be associated with tumor progression and immune suppression in lung cancer, liver cancer, and breast cancer." (PMID 38798700, 2024). "Acting as has-miRNA-944 sponge, circBACH2 attenuates the inhibitory effect of has-miRNA-944 on HNRNPC, a highly expressed m6A regulator in breast cancer, thereby boosting breast cancer proliferation and progression through promoting phosphorylation of the MAPK signaling pathway." (PMID 38075202, 2024). "Previous studies reported that hnRNPC might play a role in cancer progression, such as breast cancer and colon cancer." (PMID 34965173, 2022). "Furthermore, a recent study showed that hnRNPC deletion in human breast cancer cell lines led to splicing errors and RIG-I–dependent ISG production that was due to exposure of dsRNA-containing intronic products of the nonsense-mediated decay (NMD) machinery." (PMID 34297039, 2021). "Another study showed that the high expression of HNRNPC is significantly related to the poor OS of patients with lung adenocarcinoma, and it is likely to be an oncogene in patients with lung adenocarcinoma and breast cancer." (PMID 34054840, 2021). "Knockdown of HNRNPC inhibits cell proliferation and tumour growth of these breast cancer cells." (PMID 34044876, 2021). "HNRNPC is aberrantly up-regulated in melanoma 60, glioblastoma 61 and breast cancer." (PMID 32742465, 2020). "HNRNPC knockdown inhibits the proliferation of breast cancer cells." (PMID 31808521, 2019). "HNRNPC is thought to be a prognostic marker in tumors and has been demonstrated to be highly expressed in multiple tumors, including hepatocellular carcinoma, breast cancer, glioblastoma, and ovarian cancer." (PMID 31775888, 2019). "Furthermore, a previous study had described ISG induction in the breast cancer cell line MCF-7 targeted by hnRNPC RNA interference, which could be mildly enhanced by ADAR targeting." (PMID 34297039, 2021).
breast carcinoma (continued). "This function is conserved in other cancers; for instance, in breast cancer, WDR77 drives G1/S phase transition after being stabilized by HNRNPC." (PMID 41425556, 2025). "We have uncovered an intricate gene regulatory programme at the intersection of APA and translational control mediated by HNRNPC and PABPC4 that plays a metastasis suppressing role in breast cancer." (PMID 37156909, 2023). "Indeed, an ectopic PDLIM5 expression in HNRNPC-deficient cells was sufficient to reduce the lung metastatic burden to the levels similar to control cells with intact HNRNPC expression, in line with HNRNPC acting upstream of PDLIM5 to control breast cancer metastasis." (PMID 37156909, 2023). "By comparing tumor and normal samples, we found that six proteins were differentially expressed in breast cancer significantly (P < 0.001), including EIF3A, HNRNPA2B1, HNRNPC, RBMX, YTHDF1, YTHDF2." (PMID 33585234, 2020). "In breast cancer (BRCA), the model selected HNRNPC, IGF2BP2, IGF2BP3, FTO, METTL16, and ALKBH1." (PMID 40565233, 2025). "While some of these spliceosome genes, such as SNRPA1, SNRPD1, USP39, HNRNPU, and HNRNPC, have been shown to play an important role in promoting TNBC cell survival, proliferation, and response to chemotherapy, others are yet to be studied in breast cancer." (PMID 39418101, 2024). "Additionally, hnRNPC and hnRNPF enhanced cell survival and EMT in breast cancer and bladder cancer by controlling the stabilization of mRNAs, and the detection of hnRNPC suggests a negative prognosis in oral squamous carcinoma patients." (PMID 35875075, 2022). "Also, HNRNPC and YTHDF1 have an effect on prognosis in breast cancer patients." (PMID 34277622, 2021).
glioblastoma (26 papers, 2019 to 2025). The most malignant astrocytic tumor (WHO grade IV). "Downregulation of hnRNPC in glioblastoma inhibited its binding to miRNA-21, which suppressed the Akt pathway via upregulation the expression of programmed cell death 4 (PDCD4)." (PMID 35355828, 2022). "HNRNPC, a regulator in RNA splicing, has been upregulated in various cancers and tumor cell lines, such as glioblastoma, hepatocellular carcinoma, and lung cancer." (PMID 33692753, 2021). "Although the elevated expression of HNRNPC was incidentally observed in some cancers, including glioblastoma, hepatocellular carcinoma and melanoma, the molecular mechanism of HNRNPC in carcinogenesis has been poorly elaborated." (PMID 33952721, 2021). "A more specific example is HNRNPC, which directly binds to pri-miR-21 and promotes its expression, playing a role in the metastatic potential of the glioblastoma cell lines." (PMID 35004679, 2021). "For instance, HNRNPC was an essential participant in the malignant progression of glioblastoma and patients with high gene expression of HNRNPC were reported to have a good prognosis." (PMID 34446007, 2021). "Overexpression of HNRNPC has been observed in multiple tumors, including glioblastomas, melanomas, and hepatocellular carcinomas." (PMID 32631107, 2020). "Furthermore, HNRNPC regulates microRNA-21 (miR-21) expression, thereby affecting glioblastoma progression via Programmed Cell Death 4 (PDCD4)." (PMID 38474421, 2024). "HNRNPC shows significant expression in glioblastoma, serving as an essential splicing factor." (PMID 38474421, 2024). "In glioblastoma metastasis, the m6A reader HNRNPC directly bound to pri-miR-21 to promote miR-21 expression, whereas silencing of HNRNPC downregulated miR-21 and suppressed the AKT-p70S6K pathway, leading to the expression of PDCD4 and thus inhibiting cell migration and invasion." (PMID 32443966, 2020). "In addition, silencing of HNRNPC reduces cell proliferation and inhibits migratory and invasive activities of glioblastoma, indicating that HNRNPC serves as a promoter in multiple tumors." (PMID 33193582, 2020). "In glioblastoma (GBM), NSUN2, DNMT3B, NSUN5, TRDMT1, ALKBH1, and HNRNPC were selected." (PMID 40565233, 2025). "Notably, high expression of HNRNPC in glioblastoma enhances cell invasiveness by regulating the miR-21/PDCD4 axis, and the level of HNRNPC is reported to increase with the increasing grade of brain tumour." (PMID 35004679, 2021). "Further, we collected experimentally validated genes that could contribute to the invasive ability of glioblastoma cells (such as ZEB1, HNRNPC, WNT5A, and DRAM1) to evaluate the invasive scores for each cell (see section “Materials and Methods”)." (PMID 33505440, 2020). "Specifically, higher-grade tumors in PAAD, HNSC, Glioblastoma Multiforme (GBM), Lower-Grade Glioma (LGG), and LIHC exhibited elevated HNRNPC expression levels, while in KIPAN and KIRC, higher expression levels were associated with lower-grade tumors." (PMID 39735682, 2025). "Heterogeneous nuclear ribonucleoprotein A2B1 (HNRNPA2B1) and heterogeneous nuclear ribonucleoprotein C (HNRNPC) as the members of heterogeneous nuclear ribonucleoprotein family, have been found to be up-regulated in various types of cancers, such as liver cancer and glioblastoma." (PMID 36536402, 2022). "HNRNPC expression has been reported to be abnormal in a number of malignancies, including prostate cancer, breast cancer (BRCA), pancreatic ductal adenocarcinoma, lung adenocarcinoma (LUAD), glioblastoma, oral squamous cell carcinoma, and hepatocellular carcinoma." (PMID 35344508, 2022). "The level of HNRNPC expression in BRCA, Cholangiocarcinoma (CHOL), Colon adenocarcinoma, Esophageal carcinoma (ESCA), Glioblastoma multiforme (GBM), Head and Neck squamous cell carcinoma (HNSC), Kidney chromophobe (KICH), and Liver hepatocellular carcinoma (LIHC) was also assessed." (PMID 35344508, 2022).